IL33 (interleukin 33)
Diseases named in the same sentence as IL33 in open-access papers (continued):
Sharing a sentence is not in itself a finding about the gene and the disease.
Sepsis (continued). "Altogether these results indicate that IL-33 plays a crucial role in the expansion of ILC2s after CLP-induced sepsis, which are mediating the early production of type 2 cytokines in sepsis-surviving mice." (PMID 28374774, 2017). "Several studies have shown that IL-33 or sST2 levels are elevated in the circulation of patients with sepsis." (PMID 28168040, 2017). "At 5-10 months after sepsis diagnosis, sepsis survivors have significantly more circulating Foxp3+ Treg cells and also higher concentrations of IL-33 and IL-10 in their serum compared to those of the healthy controls." (PMID 28374774, 2017). "We then examined the potential therapeutic effect of neutralizing IL-33 in the surviving sepsis mice using the IL-33 decoy receptor, soluble ST2 (sST2)." (PMID 28374774, 2017). "In a study of sepsis, IL-33 can reverse the decreased expression of CXCR2 in neutrophils through the inhibition of GRK2." (PMID 27721573, 2016). "IL-33 has beneficial effects in experimental sepsis, enhancing the accumulation of neutrophils through the upregulation of CXCR2 via GRK2-dependent pathways at the site of infection and reducing the inflammatory response in systemic sites." (PMID 25614712, 2014). "In experimental sepsis, IL-33 has beneficial effects by enhancing the accumulation of neutrophils at the site of infection and reducing systemic but not local proinflammatory responses, resulting in an improved outcome." (PMID 22778496, 2012). "Circulating IL-33 is elevated in asthma, anaphylaxis, rheumatoid arthritis, inflammatory bowel disease and sepsis." (PMID 21949719, 2011). "IL-33, a member of the IL-1 family, is primarily produced by barrier cells such as endothelial cells, epithelial cells, and fibroblasts, which plays a dual role in sepsis." (PMID 40806563, 2025). "Further investigation of the role of IL-33 in sepsis may lead to the development of new therapeutic targets and strategies." (PMID 39991638, 2024). "In addition, during the immunosuppressive phase of sepsis, IL-33, GM-CSF or tumor necrosis factor receptor antibody (DTA-1) administration can inhibit Treg amplification and restore Th17/Treg balance, favoring the survival of sepsis." (PMID 38558800, 2024). "We analyzed whether the polymorphism was correlated with the cytokine expression of IL1β, IFNα2, IFNγ, TNF-α, IL-33, IL12p70, MCP-1, IL-6, IL-10, IL-17a, IL-18, or IL-23 to further investigate the effect of the polymorphism in sepsis patients." (PMID 38338680, 2024). "Furthermore, the CC genotype of AQP3 is accompanied by a higher expression of AQP3 and IL-33 in sepsis." (PMID 38338680, 2024). "In addition, cytokine IL-33 also upregulates Treg and contributes to sepsis-induced immunosuppression by promoting M2 macrophage polarization and IL-10 secretion." (PMID 38558800, 2024). "Furthermore, some animal experimental studies showed that IL-33 plays a protective role against sepsis." (PMID 39991638, 2024). "IL-33 seems to be important for eosinophil granulocyte function in sepsis." (PMID 38279209, 2024). "However, the exact function and potential mechanism of the IL-33 signaling pathway in sepsis remains to be elucidated." (PMID 39991638, 2024). "Previous studies described that IL-33 seemed to be protective in sepsis." (PMID 38338680, 2024). "IL-33/ST2 is a novel axis associated with poor immune function in sepsis, and this axis may benefit patients as a personalized treatment for sepsis." (PMID 38114466, 2023). "Providing clinical relevance, significantly higher concentrations of IL-33 and IL-10, as well as increased frequencies of Tregs, have been detected in the circulation of sepsis survivors sampled 5-10 months post-diagnosis when compared to age and sex-matched controls." (PMID 37662933, 2023). "IL-33 is considered an important indicator of sepsis-induced immunosuppression." (PMID 36837813, 2023). "In conclusion, the IL-33/ST2 signaling pathway could still be considered a therapeutic strategy to alleviate the symptoms of sepsis." (PMID 38082335, 2023).
Sepsis (continued). "IL-33 and sST2 levels in the circulating blood are significantly elevated during sepsis." (PMID 38082335, 2023). "Similarly, the circulating IL‐33 levels were also negatively correlated with the peak serum AST levels during sepsis." (PMID 35593197, 2022). "Thus, our findings suggest that reduced IL-33 response in sepsis in aging mice attenuates BM ILC2p mobilization and lung ILC2 recruitment." (PMID 35272622, 2022). "We found that circulating IL‐33 levels were detectable in significantly more patients in the sepsis group (77%, 10/13) than in the control group (42%, 11/26), and the serum IL‐33 levels in other patients were below the limit of detection of the enzyme‐linked immunosorbent assay (ELISA)." (PMID 35593197, 2022). "Consistent with a previous study, sepsis increased circulating IL‐33 levels." (PMID 35593197, 2022). "The level of plasma interleukin‐33 (IL‐33) is positively correlated with the severity of sepsis." (PMID 35182022, 2022). "It has been reported in some studies that IL-33 facilitates bacterial clearance by regulating neutrophil-mediated bactericidal, which may alter the course of sepsis." (PMID 35272622, 2022). "Furthermore, genetic deficiency of IL-33 and ST2 prevented sepsis-induced decreases in ILC2p in the BM and increases in the lung." (PMID 35272622, 2022). "In this study, therefore, the role of IL-33 in thepyroptosis of macrophages in the case of sepsis was deeply researched, and themechanism of IL-33 affecting the pyroptosis of macrophages was explored, so as toprovide new clues for the clinical treatment of sepsis." (PMID 34133503, 2021). "Moreover, in our recent study on a similar cohort of sepsis patients, we showed that the plasma levels of IL-8, IL-18, and IL-33 – three cytokines belonging to the IL-1-family – were significantly higher in early deceased patients compared to day 5+ survivors." (PMID 34966382, 2021). "In addition, IL-33, IL-13, and IL-5 have also been reported to prevent acute lung injury during sepsis." (PMID 34616745, 2021). "IL-33 facilitates the pyroptosis of macrophages in mice with sepsis, and increasesthe death rate of such mice by activating the NF-κB/p38 MAPK signaling pathway,providing a theoretical basis for the diagnosis and treatment of patients withsepsis in clinical practice." (PMID 34133503, 2021). "In thisstudy, IL-33-/-transgenic mice were prepared into models of sepsis, andit was found that, after modeling, the survival rate of IL-33-/-transgenic mice was dramatically increased, while the content of inflammatoryfactors and the pyroptosis level in the body were obviously reduced." (PMID 34133503, 2021). "IL-33 has been shown to promote bacteria clearance in a mouse model of sepsis." (PMID 32102434, 2020). "Therefore, sesamin pre-treatment effectively attenuated the HMGB1/TLR-4/IL-33 signalling pathway, which was enhanced by sepsis." (PMID 32893702, 2020). "Additionally, IL-33—a cytokine that plays a role in promoting Treg expansion—is elevated in septic patients, and recent studies showed neutralization of IL-33 limited the immunosuppressive effects of sepsis and improved outcomes following secondary infection." (PMID 32733454, 2020). "However, another study has shown the protective effect of the pulmonary ILC2s during sepsis-induced ALI via preventing the endothelial cell damage in response to the IL-33 released, which via binding to the ST2 receptor, mediates the ILC2 expansion." (PMID 32849610, 2020). "However, further studies are warranted to investigate the underlying mechanisms of IL-33, PGE2, IL-17A, and IL-22 in septicemia." (PMID 33178181, 2020). "Systemic IL‐33 can promote pathogen expulsion as a result of the action of ILC2s during sepsis." (PMID 32566227, 2020). "We further investigated whether sesamin can similarly alleviate LPS-induced sepsis in vitro through the HMGB1/TLR-4/IL-33 pathway." (PMID 32893702, 2020).
Sepsis (continued). "For example, increased IL-33 levels (released by epithelial cells of the lungs) in CLP-induced sepsis in mice cause sepsis-induced ALI, and IL-33 inhibition causes a decrease in sepsis-associated ALI due to the decreased neutrophil and monocyte infiltration into the lungs." (PMID 32849610, 2020). "IL-33 release is involved in the polarisation of anti-inflammatory M2 macrophages that significantly release IL-10 that in turn aids in the expansion of Tregs and ultimately contributes to the immune suppressed phase of sepsis." (PMID 33336293, 2020). "In this review, we will further discuss the individual and combined roles of IL-17, IL-27, and IL-33 during sepsis and how this axis might be therapeutically targeted." (PMID 31507598, 2019). "Moreover, increased IL-33 levels suppressed immune responses and decreased mortality in a mouse model of experimental sepsis." (PMID 31640262, 2019). "IL-33 provided a survival benefit in this model that was dependent on functional ILC2s and EOs, suggesting that IL-33 is protective in part because it re-balances type 1, 2, and 17 responses during sepsis." (PMID 31507598, 2019). "When they examined the blood of a small number of patients who had been diagnosed with sepsis 5–10 months prior, they found that sepsis survivors had significantly higher concentrations of both IL-10 and IL-33 and higher circulating Treg numbers compared to previously healthy patients." (PMID 31507598, 2019). "Indeed, the treatment with IL-33 improves the sepsis outcome due to inhibition of LPS-induced CXCR2 internalization, which maintains the neutrophil migration toward the infectious foci." (PMID 29867945, 2018). "In summary, the authors suggested a beneficial and therapeutic potential of IL-33 in sepsis." (PMID 29728738, 2018). "In the current study, we show that IL-25, IL-33, and TSLP expression increased in response to systemic inflammation caused by experimental peritonitis, and sepsis induces expansion of ILC2 in the lungs consistent with the changes in the expression of IL-25, IL-33, and TSLP." (PMID 29511181, 2018). "Here, we show that endogenous IL-33, released in response to severe tissue damage, has an essential function in the expansion of Treg cells after sepsis and in the development of long-term sepsis-induced immunosuppression." (PMID 28374774, 2017). "Moreover, sepsis-surviving patients have more Treg cells, IL-33 and IL-10 in their peripheral blood." (PMID 28374774, 2017). "Therefore, we cannot exclude the possibility that IL-33-induced MDSCs also participate in the production of IL-10 and expansion of Treg cells in sepsis survivors." (PMID 28374774, 2017). "The increased production of IL-33 in sepsis-surviving mice at a later stage of CLP prompted us to investigate whether this cytokine plays a role in the development of long-term sepsis-induced immunosuppression." (PMID 28374774, 2017). "However, IL-33-induced IL-10-secreting M2 macrophages increase the expansion of Treg cell population, thereby contributing to the development of long-term sepsis-induced immunosuppression." (PMID 28374774, 2017). "Our study suggests that targeting IL-33 may be an effective treatment for sepsis-induced immunosuppression." (PMID 28374774, 2017). "Importantly, patients who survive sepsis have more circulating Treg cells and higher concentrations of IL-33 and IL-10 in their serum compared to healthy non-sepsis individuals." (PMID 28374774, 2017). "IL-33 and sST2 serum levels were elevated in sepsis patients." (PMID 28387719, 2017). "Moreover, we show that IL-33 induces the expansion of ILC2 populations and the subsequent production of IL-4 and IL13, which together with IL-33 induce a pronounced macrophage reprogramming toward an M2-like phenotype in sepsis-surviving mice." (PMID 28374774, 2017). "Exogenous IL-33 was shown to be protective in murine models of CLP-induced sepsis." (PMID 28168040, 2017).
Sepsis (continued). "Children have significantly higher serum levels of IL-33 and sST2 on the first day of sepsis, raising the possibility that sST2 levels may be useful in the diagnosis of childhood sepsis." (PMID 28168040, 2017). "Although the results that Smaducin-6 restored LPS-induced CXCR2 reduction are similar with those recently obtained upon IL-33 treatment in sepsis, the mechanism may be different." (PMID 25766838, 2015). "This hypothesis is supported by a previous report in which IL-33 attenuates sepsis by enhancing neutrophil influx to the site of infection." (PMID 24956279, 2014). "In addition to the initiation of inflammation, IL-33 can effectively attenuate sepsis by mobilizing the innate cells, neutrophils, to the site of infection, helping to clear the pathogens." (PMID 24586149, 2014). "However, it remains to be determined in future studies if administration of IL-33 in fact represents a therapeutic strategy in the clinical treatment of patients with sepsis or SIRS." (PMID 22778496, 2012). "In contrast to sterile injury and trauma, the role of IL-33 in sepsis is better defined." (PMID 22778496, 2012). "IL-33/ST2 signaling may drive delayed immunosuppression in sepsis." (PMID 39925809, 2025). "Similarly, increased neutrophil influx into the focus of infection caused by IL-33 contributes to reducing bacterial loads was also observed when sepsis mice infected with gram-negative bacteria or acute Staphylococcus aureus." (PMID 39991638, 2024). "In addition, it is known that IL-33 is a potent activator of type 2 Innate Lymphoid Cells (ILC2), which results in enhanced production of the key effector cytokines IL-5 and IL-13, and that IL-33 plays a major role in local inflammatory changes in the lung, early after the onset of sepsis." (PMID 38279209, 2024). "IL-33 disturbs medullary thymic epithelial cell (mTEC)/cortical TEC (cTEC) compartment, which results in immunosuppression by inducing thymic involution-associated naive T cell aging and impairs host control of severe infection in mouse disease models of schistosomiasis or sepsis." (PMID 39991638, 2024). "Moreover, exogenous IL-33 treatment can increase the neutrophil influx into the peritoneal cavity, which contributes to enhancing bacterial clearance in the site of infection and reducing mortality in mice with sepsis from CLP." (PMID 39991638, 2024). "However, further research is needed to elucidate whether IL-33 can be used as a biomarker to diagnose, assess the severity, and predict the outcome of sepsis." (PMID 39991638, 2024). "Furthermore, IL-33 attenuated mortality in a murine sepsis model by promoting IFN-γ production." (PMID 38082335, 2023). "He and his team have also proposed a relationship between IL-33 and diseases such as sepsis, oncological chemotherapy, Alzheimer’s disease, and cerebral malaria, and suggest that IL-33 is a double-edged sword, the rational regulation of which may have considerable potential therapeutic effects." (PMID 37153553, 2023). "Therefore, we hypothesize that the role of IL-33 throughout sepsis changes depending on its timing and changes in the microenvironment." (PMID 38082335, 2023). "However, the protective role of IL-33 in the early stages of sepsis was abolished in later stages." (PMID 38082335, 2023). "Thus, the Th2-biased immunity initiated by IL-33 is involved with sepsis-induced immunosuppression." (PMID 37604833, 2023). "However, the role of IL-33 in ILC2 egression in sepsis has yet been studied." (PMID 35272622, 2022). "Finally, a recent study has implicated the IL–33/ST2 axis in the resolution of heightened hepatic inflammation in the context of LPS-induced sepsis, namely that IL-33 released from injured liver cells recruits ST2+ Treg cells, which then facilitate the resolution of inflammation." (PMID 35936011, 2022). "Targeting IL-33 could be another potential mechanism to treat sepsis-induced immune suppression." (PMID 33336293, 2020).
Sepsis (continued). "Therefore, in this study, we investigated the roles of sesamin in regulating the development of sepsis via the HMGB1/TLR4/IL-33 signalling pathway by examining its impacts on the production of pro-inflammatory cytokines and the expression of IL-33, HMGB1, TLR4, ZO-1, and occludin." (PMID 32893702, 2020). "Despite being linked to improvements in survival early after sepsis onset, IL-33 signaling may not always be beneficial." (PMID 31507598, 2019). "Thus, it appears that IL-33/ST2 axis may be responsible for early innate immune response to infection but also for the prolonged immunoincompetence in later phases of sepsis." (PMID 30001716, 2018). "The soluble form of the IL-33 cognate receptor, suppression of tumorogenicity (sST2), acts as a decoy receptor; the plasma concentration of sST2 is a surrogate marker of IL-33 production and a prognostic marker of sepsis, acute respiratory distress, and of heart failure." (PMID 28553430, 2017). "However, STAT6-deficiency did not reduce the amount of IL-33 in the lungs of sepsis-surviving mice, again indicating that the function of IL-33 is upstream of type 2 cytokines in the present system." (PMID 28374774, 2017). "Thus, whether the severity of septic episode would impact on the degree of the long-term immune dysfunction in sepsis survivors is currently unclear and merits further investigation together with the identification of the cellular sources of IL-33 in sepsis." (PMID 28374774, 2017). "Collectively, our results illustrate the dynamic series of molecular and cellular events in CLP-induced sepsis survivors, in which IL-33 may primarily function as an alarmin that rapidly responds to injurious signals and provides early instruction toward the repair process." (PMID 28374774, 2017). "There is also some suggestion that IL-33/ST2 may drive the delayed immunosuppression of sepsis." (PMID 28168040, 2017). "Thus, the induction and release of IL-33 during sepsis is a ‘trade-off' between the protection from an initial acute condition (such as resistance to primary infection and induction of tissue repair) and the subsequent manifestation of long-term immunosuppression." (PMID 28374774, 2017). "Increased circulating sST2 may have a negative impact on disease outcome, for example, it reduces IL-33 mediated neutrophil recruitment to the site of infection in sepsis, and is associated with poor survival after acute myocardial infarction." (PMID 21949719, 2011). "Several major DAMPs, such as eCIRP, HMGB1, histones, ATP, IL-33, eNAMPT, and RIPK3 are elevated during sepsis, hemorrhagic shock, I/R, acute pancreatitis, traumatic injury, ARDS, and pediatric diseases." (PMID 40406124, 2025). "In the early stages of sepsis, the interaction between P2X7 and Panx1 can positively regulate interleukin-33 (IL-33)." (PMID 41041630, 2025). "In contrast, exogenous IL-33 has a protective effect in mouse cecal ligation and puncture (CLP)-induced sepsis models." (PMID 39925809, 2025). "Ziehe’s results showed that the increase in IL-33 concentration was positively correlated with the expression of aquaporin-3 (AQP3), accompanied by a shortened survival period in patients with sepsis." (PMID 39991638, 2024). "The IL-33/ST2 system has also a significant role in the pathogenesis of acute and chronic inflammatory, autoimmune, and allergic illnesses, i.e., sepsis, asthma, anaphylaxis, rheumatoid arthritis, chronic obstructive pulmonary disease, etc.." (PMID 38152329, 2023). "We found an increase in the expression of IL-6, IL-8, IL-10, IL-18, IL-33, IP-10, MIF, MIP1a, MIP1β, MIP3a, LEPTIN, GCSF, MCSF, and ESelectin in sepsis plasma compared to w/o sepsis and HC." (PMID 35681439, 2022). "However, the role of IL-33 in ILC2 egression from BM in sepsis remains unclear." (PMID 35272622, 2022). "To determine the role of CXCR4 signaling in ILC2p egress from the BM following sepsis, we first measured cell surface expression of CXCR4 on ILC2p in BM from WT and Il33−/− mice." (PMID 35272622, 2022).